EMD (emerin)
Diseases named in the same sentence as EMD in open-access papers (continued):
Sharing a sentence is not in itself a finding about the gene and the disease.
tumor (18 papers, 2011 to 2025). "Our data demonstrate that siRNA-mediated depletion of Ankle2, Emerin, and Lemd2 inhibits cell proliferation in a largely tumor-specific manner in TNBC cells." (PMID 38720803, 2024). "The identified splice variant genes (CENPK, PKN1, KIAA1324, EMD, and TSC2) associated with response were mainly related to mitosis, PI3K–Akt cell survival/proliferation signaling, and tumor progression and metastasis." (PMID 39404386, 2024). "Emerin mislocalization corresponds with increases in the migratory and invasive potential of tumor cells, especially in a collagen-rich microenvironment." (PMID 39218980, 2024). "First, the EMD gene was silenced in HL‐1 (derived from AT‐1 mouse atrial cardiomyocyte tumour cell line) and H9C2 (derived from embryonic BDIX rat heart) cells using adenovirus and specific siRNA, respectively." (PMID 36106556, 2022). "Emerin has been shown to be dynamically expressed in a wide variety of tumours, with its expression being significantly decreased in highly metastatic tumours." (PMID 36205821, 2022). "Decreased Lamin A/C and Emerin expression tends to be correlated with tumor grade in osteosarcoma cell lines." (PMID 36561231, 2022). "A-type lamins also influence the activity of oncogene β-catenin (via the interaction of the membrane protein emerin with the Wnt/β-catenin pathway) which also points to a possible role of A-type lamins in tumor progression." (PMID 24392146, 2014). "The dysregulated phosphorylation of emerin in MECMECs could disrupt normal cellular functions and contribute to tumorigenic signaling pathways by modulating the accessibility of oncogenes and tumor suppressors." (PMID 40478494, 2025). "However, it has been previously shown that Emerin directly binds beta-catenin, a signaling factor of the Wnt pathway which is commonly dysregulated in tumor cells." (PMID 38720803, 2024). "GFP-Emerin overexpression has also been shown to decrease tumor size in mice models." (PMID 38720803, 2024). "Thus, in the present study, we analyzed how Lamin A and Emerin contribute to tumor progression in human IPMN cases." (PMID 36561231, 2022). "Several recent studies suggest that Lamin and Emerin expression is involved in tumor malignancy." (PMID 36561231, 2022). "Taken together, all of these results strongly implicated that ANKLE1, EMD, and LEMD2 could serve as major tumor immune infiltration regulators in PRAD." (PMID 35650630, 2022). "It will be important to determine whether emerin expression is different between metastatic subpopulations compared to the primary tumor." (PMID 34681951, 2021). "Our findings build upon the existing knowledge of the roles of Lem-D proteins in tumor cells and demonstrate the role of several Lem-D proteins: Ankle2, TMPO, Emerin, and Lemd2 in TNBC growth and cell survival." (PMID 38720803, 2024). "Among all LEMs, only the expressions of ANKLE1, EMD, and LEMD2 were correlated with advanced tumor stage and survival prognosis in PRAD." (PMID 35650630, 2022). "Among the top five growth-suppressing genes tested, STARD8 and DUSP6, a commonly known tumor suppressor, arrested cells in G1/G0-phase, while MAPRE3, RPS6KA2 and EMD induced apoptosis." (PMID 28423600, 2017). "Emerin mislocalization was previously reported in 80 PCa cases, where it discriminated tumor tissue from nontumor tissue and was correlated with disease progression." (PMID 39218980, 2024). "This study further found a new mechanism that ANKLE1, EMD, and LEMD2 expressions may affect the prognosis of PRAD through tumor immune infiltration." (PMID 35650630, 2022). "In addition, we examined the prognostic value of ANKLE1, EMD, and LEMD2 levels and tumor-infiltrating resting NK cells in PRAD, using the Cox proportional hazard model by TIMER." (PMID 35650630, 2022).
infection (8 papers, 2011 to 2025). The state of being infected such as from the introduction of a foreign agent such as serum, vaccine, antigenic substance or organism. "Both lamin B and the lamina-associated protein emerin are phosphorylated during infection, leading to the loss of connections between emerin and the nuclear membrane." (PMID 21994768, 2011). "The cleaved EMD N-terminal fragment is detected and moderately stable during infection." (PMID 38953667, 2024). "(H) HSV-1 sgRNA- or ctrl sgRNA-expressing dCas9-emerin cells were treated with sodium butyrate (NaB) for 5 hr before infection (red lines) or not treated (black lines)." (PMID 37702383, 2023). "Full-length RAI but not EMD protein levels decreased during infection." (PMID 38953667, 2024).
genetic disorders (6 papers, 2019 to 2025). "Emery–Dreifuss syndrome is a rare genetic disease, caused by mutations of emerin (EMD) and lamin A/C (LMNA) genes, and can be autosomal dominant or recessive." (PMID 34356086, 2021). "Although mutations in the human EMD gene are most closely tied to the genetic disorder EDMD1, similar phenotypes arise from mutations in genes coding for interacting proteins, such as LMNA, SYNE1, SYNE2, and TMEM43." (PMID 30871242, 2019). "Mutations in the human EMD gene coding for emerin result in the rare genetic disorder: Emery–Dreifuss muscular dystrophy type 1 (EDMD1)." (PMID 30871242, 2019). "Mutations in the human EMD gene coding for emerin result in the genetic disorder Emery–Dreifuss muscular dystrophy type 1 (EDMD1, OMIM 310300)." (PMID 30871242, 2019). "Emery–Dreifuss muscular dystrophy type 1 (EDMD1) is a rare genetic disease caused by mutations in the EMD gene, which encodes the nuclear envelope protein emerin." (PMID 40004006, 2025).
myopathy (5 papers, 2019 to 2025). A disease of the muscle in which the muscle fibers do not function properly. "However, LAP1 and emerin double-KO mice showed exacerbated myopathy, suggesting that LAP1 and emerin may have compensatory functions in myocytes." (PMID 36960155, 2023).
cardiac disease (3 papers, 2019 to 2025). "The degree of neuromuscular involvement in EDMD1 shows both inter- and intrafamilial variability and there are reports of cardiac disease being the predominant manifestation in males harboring EMD variants." (PMID 40065010, 2025). "Novel human variants identified in this study provide new tools to study their molecular roles and potential association with adult-onset heart disease or new physiological roles, as reported here for ‘healthy lipid’ emerin variant p.D149H." (PMID 31024910, 2019). "Molecular detection can be determined in EMD and FHL1 pathogenic variants for asymptomatic patients because heterozygous women are at risk of developing heart disorders and muscular dystrophy syndromes." (PMID 34356086, 2021).
metabolic disease (2 papers, 2019 to 2026). A congenital disorder (due to inherited enzyme abnormality) or acquired (due to failure of a metabolically important organ) disorder resulting from an abnormal metabolic process. "These traits are distinct from LMNA-associated metabolic disorders and provide the first insight that emerin influences metabolism." (PMID 31024910, 2019).
cardiovascular disease (1 paper, 2018). "Mutations of the following genes can lead to cardiovascular disease: Filamin A, EMD (emerin), LAMP2 (lysosomal-associated membrane protein 2), DMD (dystrophin), TAZ (tafazzin), and VEGF-D (vascular endothelial growth factor D)." (PMID 30459711, 2018).
epithelial carcinoma (1 paper, 2022). "Of note, plasmid-mediated overexpression of DUX4 in human epithelial carcinoma HEp-2 cells leads to mis-localization of the inner nuclear envelope protein, emerin." (PMID 35191484, 2022).
neuromuscular disease (1 paper, 2023). "Of the patients with diagnostic variants, 1.6% (8/514) had a variant in genes (DMD and EMD) associated with neuromuscular diseases." (PMID 37795486, 2023).
prostate (1 paper, 2024). "To extend the analysis of NE proteins during prostate carcinogenesis, we evaluated the subcellular localization and protein expression of the inner nuclear membrane proteins emerin and β-DG, which are also nuclear lamina-associated proteins." (PMID 39115711, 2024).
EMD also shares sentences with these, for which no sentence is quoted: dilated cardiomyopathy (7 papers); progeria (3); diarrhoea (2); Nestor-Guillermo progeria syndrome (2); atrial fibrillation (1); autosomal dominant Emery-Dreifuss muscular dystrophy (1); Barth syndrome (1); benign prostatic hyperplasia (1); cardiac hypertrophy (1); Coffin-Lowry syndrome (1); collagen vascular disease (1); colorectal adenocarcinoma (1); congenital muscular dystrophy (1); Cornelia de Lange syndrome (1); Danon disease (1); deafness (1); diabetes (1); Duchenne muscular dystrophy (1); escherichia coli infection (1); Holt-Oram syndrome (1); Hutchinson-Gilford progeria syndrome (1); Insulin resistance (1); intellectual disability syndrome (1); LEOPARD syndrome (1); limb -girdle muscular dystrophy type 1B (1); long QT syndrome (1); malabsorption syndrome (1); Marinesco Sjögren syndrome (1); metabolic syndrome (1); motor neuron diseases (1).
A further 11 diseases each share a sentence with EMD in 1 paper.